PNISR (PNN interacting serine and arginine rich protein)
Synonyms: SRrp130; C6orf111; SFRS18; HSPC306; FLJ14752; bA98I9.2; DKFZp564B0769
Tractability: Antibody: its Gene Ontology location is reachable by antibodies, with high confidence. PROTAC: UniProt records ubiquitination sites on it; ubiquitination databases record sites on it; its protein half-life has been measured.
Gene: Protein-coding gene on chromosome 6 (99,397,629 to 99,425,335, reverse strand). Ensembl gene ENSG00000132424.
Subcellular location: Nucleus speckle
Subcellular location (Human Protein Atlas): Nuclear speckles; Cytosol; Plasma membrane
Gene Ontology:
Molecular function: RNA binding
Cellular component: nuclear speck; presynaptic active zone
Genetic constraint (gnomAD): Loss-of-function variants: 12 observed, 50.03 expected, observed/expected ratio (o/e) 0.24, 90% interval 0.15 to 0.39. The upper end of that interval is the gene's LOEUF score, 0.39, which puts it in group 1 of 6, group 1 being the genes least tolerant of losing a copy. Missense variants: 581 observed, 672.07 expected, observed/expected ratio (o/e) 0.86, 90% interval 0.81 to 0.93. Synonymous variants: 212 observed, 217.77 expected, observed/expected ratio (o/e) 0.97, 90% interval 0.87 to 1.09.
Homologues: Orthologues: chimpanzee PNISR (99% identical), macaque PNISR (99% identical), dog PNISR (99% identical), pig PNISR (98% identical), rabbit PNISR (97% identical), guinea pig PNISR (96% identical), rat Pnisr (94% identical), mouse Pnisr (93% identical), zebrafish pnisr (57% identical), Drosophila melanogaster CG31211 (23% identical), Caenorhabditis elegans rsy-1 (21% identical).
Diseases named in the same sentence as PNISR in open-access papers:
PNISR is named in the same sentence as 7 diseases in open-access papers, as found by Europe PMC text mining. Sharing a sentence is not in itself a finding about the gene and the disease. The quoted sentences say what the papers report.
cognitive deficits (1 paper, 2023). "RBM5, PNISR (also known as SFRS18) and HNRNPM code for RNA-binding proteins, and dysregulations of these genes are associated with carcinogenesis, psoriasis and cognitive deficits, respectively." (PMID 37026480, 2023).
myasthenia gravis (1 paper, 2019). Myasthenia gravis (MG) is a rare, clinically heterogeneous, autoimmune disorder of the neuromuscular junction characterized by fatigable weakness of voluntary muscles. "By comparing transcriptome of thymoma with and without myasthenia gravis, we found that 5 genes (PNISR, CCL25, NBPF14, PIK3IP1 and RTCA) were upregulated more than 2-fold, and that more than 30 genes were downregulated more than 2-fold." (PMID 30787364, 2019).
virus infection (1 paper, 2022). "NKT cells of the peripheral blood in C. carbonaria were identified by PITPNM2, OGT, PRPF4B, PNISR, and CD3E genes, which had immunoregulatory roles in virus infection and cancer." (PMID 36552787, 2022).
cancer (2 papers, 2020 to 2022). A tumor composed of atypical neoplastic, often pleomorphic cells that invade other tissues. "We also identified 5 genes (LGR4, RARG, PNISR, PCOLCE2, RALGDS) that shared the same patterns across three types of cancer, and 39 genes with two overlaps across eight cancer types." (PMID 32764426, 2020).
PNISR also shares sentences with these, for which no sentence is quoted: lymphoid leukemia (1 paper); psoriasis (1); thymoma (1).